RNU6-1214P (RNA, U6 small nuclear 1214, pseudogene)
Gene: Small nuclear RNA gene on chromosome 4 (139,318,378 to 139,318,486, forward strand). Ensembl gene ENSG00000200520.
Homologues: Orthologues: chimpanzee U6 (100% identical), dog U6 (87% identical), guinea pig U6 (81% identical), mouse Gm25565 (75% identical). Paralogues in human: RNU6-1145P (91% identical), RNU6-38P (89% identical), RNU6-639P (87% identical), RNU6-1084P (86% identical), RNU6-1158P (86% identical), RNU6-1316P (86% identical), RNU6-20P (86% identical), RNU6-333P (86% identical), RNU6-393P (86% identical), RNU6-39P (86% identical), RNU6-476P (86% identical), RNU6-1031P (85% identical), and 1287 more.